LGR5 (leucine rich repeat containing G protein-coupled receptor 5)
Diseases named in the same sentence as LGR5 in open-access papers (continued):
Sharing a sentence is not in itself a finding about the gene and the disease.
adenoma (continued). "To test whether stem cell-specific Brg1 loss could attenuate Wnt-driven adenoma formation we intercrossed mice expressing the GFP-IRES-CreERT2 knock-in allele under control of the Lgr5 promoter (further abbreviated as Lgr5-GFP-CreERT2) with animals bearing targeted Apc and Brg1 alleles." (PMID 25010414, 2014). "Thus the transition from adenoma to carcinoma may involve selective loss of LGR5 in areas of wnt hyperactivation, contributing to EMT and invasiveness." (PMID 21829496, 2011). "Conversely, the Lgr5 ISC cluster was significantly enriched in Smad4+/+ (5.8%) compared to Smad4fl/fl adenoma (2.7%)." (PMID 40348815, 2025). "The Wnt dependent intestinal stem cell marker Lgr5 was downregulated in Smad4+/+ following TGF-β1 (12 h) compared to Smad4Δ/Δ adenoma (2 log2FC), also suggesting modification in Wnt pathway activity." (PMID 40348815, 2025). "The co-expression of IL-8RA and IL-8RB with CD34+ tumor-associated microvessels in both the adenoma and CRC or with LGR5 labeled cancer stem-like cells (CSCs) in CRC tissue sections." (PMID 40149674, 2025). "Clonal fate tracing and retracing analyses revealed that Lgr5+ cells residing in the base of an adenoma segment can undergo self-renewal and differentiation into several cell types, providing more definitive evidence that Lgr5 is a marker of adenoma CSCs." (PMID 38254219, 2024). "Lgr5-Cre:Pik3caH1047R:Apc580D/580D parental tumours were classified as adenomas displaying high-grade dysplasia throughout the polyp mass." (PMID 39093890, 2024). "This was demonstrated in the mouse intestine where loss-of-function mutations in the Apc tumor suppressor gene successfully initiate adenoma formation only when they occur in Lgr5+ intestinal stem cells (ISCs)." (PMID 38902475, 2024). "In FAP NM tissues Ki67 expression slightly decreased compared to FIT+ (fold: 0.4) while LGR5 expression slightly increased (fold: 1.5) but appeared significantly lower than the adenoma group (P = .019)." (PMID 38970018, 2024). "The opposite was observed for DCLK1 (doublecortin-like kinase 1), a Tuft19 and tumor stem cell marker, that was more frequently detected among PC-derived adenomas (Lyz1/Apc: 54.1% ± 10.5%) when compared with Lgr5-derived tumors (Lgr5/Apc: 15.6% ± 15.7%)." (PMID 38902475, 2024). "Changes in BA profiles lead to malignant transformations in Lgr5-expressing (Lgr5+) cancer stem cells and promote adenoma-to-adenocarcinoma progression." (PMID 38731514, 2024). "A lineage-tracing study using a multicolor Cre-reporter model showed that the Lgr5+ stem cells, only representing 5–10% of the adenoma cells, generated additional Lgr5+ cells and other adenoma cell types, indicating that tumors are initiated in Lgr5+ cells." (PMID 37746286, 2023). "Lgr5+ stem cells can form gradually proliferating adenomas on abnormal Wnt pathway activation, indicating that Lgr5+ cells were the cells-of-origin of colorectal tumors." (PMID 37667332, 2023). "Specimens of adenoma with high grades of dysplasia were more likely to express moderate-to-strong expression of LGR5." (PMID 37512045, 2023). "The expression of c-Myc is significantly higher in adenocarcinoma organoids than in adenoma organoids while the expression of the LGR5 and OLFM4 in adenocarcinoma organoids is extremely low." (PMID 37667332, 2023). "The secondary bile acid, deoxycholic acid (DCA), induces DNA damage and proliferation in Lgr5+ cancer stem cells and promotes adenoma-to-adenocarcinoma progression." (PMID 36624306, 2023). "We next extended our analysis to wild-type small intestine or Apc-mutant adenomas from Lgr5-EGFP-Ires-CreERT2/Apcfl/fl/R26R-Confetti mice (dataset GSE37929)." (PMID 36765930, 2023). "In the twelve cases of adenoma, the LGR5 and Β-catenin expressions were moderate in 6/12 (50%) of the cases." (PMID 37512045, 2023). "The well-characterized deregulation of Wnt/Β-catenin signaling that occurs during adenoma/carcinoma sequence in CRC renders LGR5 a hopeful therapeutic target." (PMID 37512045, 2023).
adenoma (continued). "The opposite was observed for Dclk1 (doublecortin like kinase 1), a Tuft20 and tumor stem cell marker, that was more frequently detected among PC-derived adenomas (Lyz1/Apc: 54.1 % ± 10.5) when compared with Lgr5-derived tumors (Lgr5/Apc: 15.6 % ± 15.7)." (PMID 36711533, 2023). "Beyond its well-established role in regulating cytotoxicity of hydrophobic BAs, early study has highlighted the role of FXR in restricting the tumorigenesis of Lgr5+ cells, which mediate the key adenoma-to-adenocarcinoma transformation." (PMID 38069256, 2023). "This was demonstrated in the intestine where loss-of-function mutations in the Apc tumor suppressor gene successfully initiate adenoma formation only when they occur in Lgr5+ CBCs." (PMID 36711533, 2023). "Recent studies have found that the Lgr5+ stem cell population is logarithmically expanded in murine and human adenomas and carcinomas and correlates with poor CRC prognosis." (PMID 35260534, 2022). "Further analysis revealed that increased populations of LGR5 and aldehyde dehydrogenase 1 (ALDH1) labeled SCs in the adenoma were associated with the degree of dysplasia, suggesting the involvement of SCs in the establishment of adenomas." (PMID 36466926, 2022). "In line with this, Lgr5+ cells in the adenomas were pPDH−, consistent with what we observed in normal epithelium (, e)." (PMID 35314684, 2022). "Recent studies identify the Lgr5+ stem cell as a potential cell of origin for mouse adenoma development and human CRC." (PMID 35260534, 2022). "For example, CD44v expression was identified in Lgr5+ ISCs and contributes to adenoma formation in ApcMin/+ mice as a Wnt signal target gene." (PMID 34971821, 2022). "In contrast, in the absence of exogenous Wnt, Ade1 and Ade2 contained 65.4% ± 1.0% and 64.1% ± 1.1% Lgr5+ cells, respectively, similar to the logarithmic increase seen in human adenomas." (PMID 35260534, 2022). "In order to assess the effect of BVDU on adenoma formation, we used Lgr5‐CreERT2;Apcfl/fl mice, that allow for low‐dose recombination of Apc in the stem cell compartment and therefore is a more controlled model of intestinal transformation." (PMID 36321561, 2022). "Extensive co-expression of Thbs1 and Lgr5 in adenomas is accompanied by the presence of large tumour regions rich in cells presenting nuclear YAP, which were not visible in invasive adenocarcinomas." (PMID 35543624, 2022). "CD44v6 and other ‘variable’ CD44 isoforms (CD44v4-10) earmark Lgr5+ intestinal stem cells (ISCs), that is, the cells of origin of intestinal tumors, and accordingly promote adenoma formation in vivo." (PMID 36346211, 2022). "In the (micro)adenomas that formed in the ApccKO/cKO Lgr5-CreERT2-EGFP mice three weeks after Apc gene inactivation, we also observed that some areas of the tumors produced Trop2." (PMID 36077674, 2022). "Lgr5-positive areas were increased in intestinal adenomas of Mir34aΔIEC;ApcMin/+ mice and decreased in adenomas of Csf1rΔIEC;ApcMin/+ mice." (PMID 36147476, 2022). "In order to assess effects on tumor cell stemness, we determined the expression of the stem cell marker Lgr5 in adenoma sections using in situ hybridization (ISH)." (PMID 36147476, 2022). "In the normal gut and adenomas, active, “working” Lgr5+ stem cells are located next to the Paneth cells, which provide essential niche factors for the stem cells." (PMID 34788095, 2021). "The experiments in mouse models showed that the Lgr5+ stem cells can increase additionally the population of Lgr5-positive cells and drive adenoma expanding in colon." (PMID 34381360, 2021). "We found that approximately 10 and 40% of Lgr5+ cells were located next to Lyz1+ cells in the LApc and LApcL adenomas, respectively, suggesting that the Lgr5+ ISCs give rise to the strongly increased ectopic crypts after Lef1 deletion." (PMID 34788095, 2021). "We found that Lef1 deletion increased Lyz1+ cells but, unexpectedly, decreased Lgr5+ stem cells in the LApcL adenomas." (PMID 34788095, 2021).
adenoma (continued). "In conventional adenomas, expression of LGR5 is spread throughout the gland, suggesting an expanded niche and the lack of a cellular hierarchy." (PMID 33673710, 2021). "Western blots show that 5-ASA suppresses expression of LGR5 in 2/3 adenomas, the transformed adenoma and both CRC-derived cells, over a 72-h period." (PMID 33785874, 2021). "Although Lef1 deletion in the tumors decreased the number of Lgr5+ adenoma stem cells, it simultaneously increased the number of ectopic stem cell niches." (PMID 34788095, 2021). "The distribution of the LGR5 gene expression increase in adenomas indicates that a stem cell/progenitor cell hierarchy is preserved in early neoplastic lesions." (PMID 34452555, 2021). "Downregulation of β-catenin was found to repress expression of stem cell marker LGR5 (leucine-rich G protein-coupled receptor-5) and functionally suppress stemness in human adenoma and carcinoma cells using 3D models of tumorigenesis." (PMID 33785874, 2021). "Using an Apc knock-in mouse model, Barker and colleagues demonstrated that only Apc mutant Lgr5+ cells can form adenomas." (PMID 34071313, 2021). "We found a substantial increase in Lyz1+ cells and doublets of Lyz1+ and Lgr5+ cells that appeared to form intestinal crypt-like structures in β-catenin+ adenomas after Lef1 deletion." (PMID 34788095, 2021). "Since deletion of Nedd4 and Nedd4l increases ISC numbers under homeostasis, we further examined the ISC marker Lgr5 expression in control and mutant adenomas." (PMID 31867777, 2020). "It has been pointed out that there is a difference in LGR5 expression between the adenoma–carcinoma sequence and the serrated neoplasia pathway in RNA in situ hybridization." (PMID 32293346, 2020). "Ablation of Apc (adenomatous polyposis coli) gene in Lgr5-expressing cells leads to macroscopic adenomas and intramucosal well-differentiated carcinoma." (PMID 33043003, 2020). "CRC should be divided into MMR-D cases involving the serrated neoplasia pathway and MMR-P cases involving the adenoma–carcinoma sequence if LGR5 is used as a prognostic marker, and LGR5 should be evaluated by RNA in situ hybridization." (PMID 32293346, 2020). "The genetic ablation of Mll1 in mice prevents Wnt/β-catenin-driven adenoma formation from Lgr5+ intestinal stem cells." (PMID 33349639, 2020). "This showed that also in adenomas the Lgr5+ cell population in the bottom of glands, display a similar repopulating potential as their normal counterparts within the glandular structures." (PMID 30927915, 2019). "Upon adenoma initiation in Lgr5+ cells, lineage tracing was performed by so-called ‘re-tracing’ of the Lgr5+ population in established adenomas." (PMID 30927915, 2019). "Because the loss of Sh3bp4 alone caused ISC expansion, we further analyzed the stem cell marker Lgr5 expression in Apcmin and ApcminSh3bp4 cKO adenomas." (PMID 30811977, 2019). "Consistent with the Sh3bp4 cKO phenotype, a significant increase in Lgr5-expressing stem cells was observed in the ApcminSh3bp4 cKO adenomas." (PMID 30811977, 2019). "This is in contrast with the percentage of Lgr5+ cells that is found within the adenomas, approximately ~ 20% of the total population (~ 400 cells per gland)." (PMID 30927915, 2019). "Igf2rI1565A/+p in a conditional model (Lgr5-Cre, Apcloxp/loxp) resulted in worse survival and increased adenoma proliferation." (PMID 31388182, 2019). "Consistently, simultaneous deficient of these two E3 ligases in the intestinal epithelium induced the formation of unusual adenomas consisting entirely of Lgr5+ stem cells and their niche." (PMID 31905853, 2019). "The proliferative response increased by LGR5 suppression potentiates EGFRi sensitivity and death of adenoma cells (in keeping with the proliferative capacity of aggressive tumours rendering them more sensitive to anticancer agents)." (PMID 29149105, 2018).
adenoma (continued). "Vitally, our studies have also indicated a novel role for LGR5 expression in the sensitivity of adenoma cells to EGFR inhibitors such as gefitinib." (PMID 29149105, 2018). "The deletion of Ap4 in these tumor organoids was accompanied by lower levels of the ISC markers Smoc2, Lgr5 and Olfm4 when compared with Ap4 wild-type adenomas." (PMID 30177706, 2018). "To assess the effect of EGF on LGR5+ cells at an early stage of CRC we required a physiologically relevant in vitro adenoma model that exhibited EGF-sensitivity." (PMID 29149105, 2018). "Taken together these data indicate that suppression of LGR5 enhances the proliferative capacity of EGF-treated adenoma cells." (PMID 29149105, 2018). "To understand the basis for the reduced survival of EGF-treated adenoma cells upon LGR5 knockdown, we next examined expression levels of the Ki67 proliferation marker." (PMID 29149105, 2018). "Detached cell yield was higher in RG/C2 adenoma cells treated with EGFRi but this was significantly enhanced by combination with LGR5 siRNA at both 24 and 48 h." (PMID 29149105, 2018). "Suppression of LGR5 reduces the survival of EGF-treated adenoma cells by increasing detached cell yield but also inducing a proliferative state, as evidenced by elevated Ki67 level and enhanced cell cycle progression." (PMID 29149105, 2018). "Conditional deletion of both Znrf3 and Rnf43 from the intestinal epithelium induces rapid expansion of Lgr5+ ISCs and subsequent hyperactivation of Wnt signalling, quickly leading to adenoma formation." (PMID 29570681, 2018). "In intestinal adenomas, Lgr5+ CSCs have been found to maintain contact with Paneth cells to fuel adenoma development and replenishment." (PMID 30389919, 2018). "To understand the basis for the heightened proliferative state of EGF-treated adenoma cells upon LGR5 suppression, we next analysed cell cycle status." (PMID 29149105, 2018). "These LGR5+ cells represent 5–10% of the cells in the mouse adenomas and generate other LGR5+ cells, as well as other cell types composing the adenoma." (PMID 29652830, 2018). "Similar to normal murine organoids, we noted an increase in LGR5 expression following EGF withdrawal from 3D adenoma culture medium." (PMID 29149105, 2018). "Epidermal growth factor and gefitinib treatments were performed in EGF-responsive LGR5+ early adenoma RG/C2 cells." (PMID 29149105, 2018). "Like wild-type intestinal stem cells, Lgr5 positive adenoma stem cells reside in the bottom of the crypt niche, where they generate aberrantly proliferating Lgr5-negative adenoma cells that build the tumor mass." (PMID 28356110, 2017). "Here, we showed, using the multicolor lineage-tracing method and mouse models of intestinal adenocarcinoma and adenoma that Bmi1- or Lgr5- positive tumorigenic cells clonally expanded in proliferating tumors." (PMID 28176811, 2017). "FAP mice contained Lgr5+ adenoma cells colocalized with Paneth cells as well as with other cell types." (PMID 28176811, 2017). "Both of these studies suggest that constitutive activation of the intestinal SC program is sufficient for rapid and efficient malignant transformation of murine LGR5+ colon stem cells and LGR5− differentiated colon cells into murine adenomas." (PMID 26744320, 2016). "Stem-like cancer cells (CSCs) in CRC are marked by Lgr5 and such Lgr5-marked CSCs are present at high levels in human adenomas and invading cells." (PMID 26862851, 2016). "Second, we performed immunohistochemical analysis of adenoma tissue that developed in induced Lgr5-CreER." (PMID 26956214, 2016). "As expected, the mRNA level of the wild-type Apc (ApcWT) was significantly decreased, whereas that of Lgr5, an established intestinal stem cell marker, was increased in adenoma cells, suggesting successful isolation of adenoma cells and normal cells." (PMID 27589228, 2016). "This is consistent with the finding that targeted APC deletion in murine LGR5+ colon SC gave rise to adenomas." (PMID 26744320, 2016).
adenoma (continued). "Loss of Rnf43 and Znrf3 expression results in hyperresponsiveness to Wnt signals leading to the formation of abnormal adenomas consisting entirely of Lgr5 stem cells." (PMID 27187360, 2016). "We observed that, similar to normal crypts, BCL-2 expression matches Lgr5-GFP expression suggesting a specific role of Bcl-2 in stem-like cells in adenomas." (PMID 26956214, 2016). "Since LGR5 promotes malignant transformation and increases the intestinal SC gene signature, LGR5+ colon SC is likely the predominant adenoma-initiating cell for the development of a human colon adenoma." (PMID 26744320, 2016). "Here we used in situ hybridization to specifically examine LGR5 mRNA expression in a panel of human adenoma and carcinoma samples (n = 66)." (PMID 25728748, 2015). "Rapidly growing adenomas form in the mouse after deletion of APC in LGR5+ intestinal stem cells, suggesting that normal stem cells are the cell-of-origin of intestinal cancer." (PMID 25751518, 2015). "Here we use ISH to systematically study the localization of LGR5 expressing cells in human hyperplastic polyps, adenomas of different histological sub-types and adenocarcinomas of all stages, with the aim to detect alterations in their stem cell architecture." (PMID 25728748, 2015). "Immunohistochemical analysis of GFP expression in small intestinal tumours detected GFP positive cells in both macro and micro adenomas, implying activity of the Lgr5-GFP-CreERT2 transgene and stem cell origin of both types of lesions." (PMID 25010414, 2014). "In the basal pattern tumors, the Lgr5+ cells were mostly restricted to the base of the adenoma segment, which was reminiscent of both IM and the normal crypt architecture." (PMID 24340024, 2013). "LGR5 expression was higher in low-grade adenomas than in high-grade adenomas (p = 0.025), and the expression tended to decline with tumor dedifferentiation (p = 0.036)." (PMID 24340024, 2013). "In this respect, it is interesting to note that paneth-like cells have been reported in mouse adenomas and reside in close proximity to the LGR5+ adenoma stem cells." (PMID 24144042, 2013). "In particular for the APC model, it has been shown that deletion of APC specifically in LGR5-positive cells is sufficient to give rise to adenomas within 3–5 weeks." (PMID 22848656, 2012). "The expression of LGR5 in intestinal stem cells, its dependence on activated wnt signalling, and its link to cell invasiveness position LGR5 as a potential player in the transition from adenoma to invasive carcinoma." (PMID 21829496, 2011). "While Wnt activation maintains Lgr5+ ISCs in mammals and Apc mutations cause undifferentiated adenomas, Wnt pathway knockdown does not notably affect ISC numbers in adult Drosophila midguts." (PMID 41337595, 2025). "Dysregulated Wnt signaling due to Apc mutation can also alter bile acid profiles and increase levels of tauro-β-muricholic acid and deoxycholic acid to drive malignant transformations in Lgr5-expressing (Lgr5+) cancer stem cells and promote a progression from adenoma to adenocarcinoma." (PMID 38590663, 2024). "Of note, while cells expressing the PC marker lysozyme (Lyz1) were notable in Lgr5-derived tumors (Lgr5/Apc: 30.0 % ± 18.5 positive tumor cells), they were nearly absent in adenomas that originated from Paneth cell mutation (Lyz1/Apc: 0.48 % ± 1.16)." (PMID 36711533, 2023). "In particular, given that LGR5 is also expressed in scattered cells in pre‐malignant mouse adenomas, TiO2 NPs could potentially be applied to inhibit the progression of diseases in which Lgr5+ cells play essential roles." (PMID 36798041, 2023). "Additionally, although recent research identifies the Lgr5+ stem cells as the possible cells of origin for the formation of mice adenoma and human CRC, the proportion of Lgr5+ CSCs in CAC is one third less than in CRC." (PMID 36672697, 2023).